LEP (leptin)
Diseases named in the same sentence as LEP in open-access papers (continued):
Sharing a sentence is not in itself a finding about the gene and the disease.
Insulin resistance (continued). "Treatment with sitagliptin ameliorated body weight gain, lipid metabolic disorder, and steatosis as well as hepatic insulin resistance in leptin-deficient ob/ob mice by inhibiting inflammatory responses and activating autophagy through the AMPK/mTOR pathway." (PMID 37739179, 2023). "The reduced phosphorylation of JAK2 and STAT3 in LEPTIN deficient pig livers led to hepatic insulin resistance and increased fat synthesis marked by activation of SOCS3 and SREBP-1c, respectively, further confirms the value of the pig model." (PMID 37705071, 2023). "Adipocyte hypertrophy is associated with reduced secretion of leptin and adiponectin, together with enhanced secretion of insulin resistance inducers, blood coagulation promoters, monocyte chemoattractant proteins, and angiotensinogen." (PMID 37107219, 2023). "Increased plasma PAI-1 is associated with insulin resistance in people, and has been shown to cause insulin resistance in rodent models, and the plasma leptin/adiponectin concentration ratio correlates with insulin resistant glucose metabolism in people." (PMID 37159276, 2023). "Another animal study in leptin-deficient ob/ob mice showed that liver-specific inhibition of ChREBP improves hepatic steatosis and insulin resistance." (PMID 37998747, 2023). "Insulin resistance can cause adipose tissue to secrete leptin, IL-6, TNF-α and other adipocytokines, and interact with these factors to cause the ‘second hit’, in which TNF-α plays a key role in this stage." (PMID 38041076, 2023). "It is stated that elevated leptin levels are linked to the presence of insulin resistance and reduced adiponectin levels, with increasing levels of fasting blood sugar level promoting the onset of diabetes." (PMID 37444627, 2023). "Reduced adiponectin and elevated leptin plasma levels have been associated with developing insulin resistance." (PMID 36838843, 2023). "Leptin-deficient mice (Ob mice) show hyperphagia, insulin resistance, hyperinsulinemia, and infertility." (PMID 38139229, 2023). "Other possible explanations for the inverse association between FM and BMD involve leptin, insulin resistance, vitamin D status and lifestyle factor." (PMID 36926024, 2023). "Leptin and adiponectin are adipokines that have been linked to insulin resistance and an increased risk of developing diabetes." (PMID 37724233, 2023). "High concentrations of resistin and leptin and low concentrations of adiponectin are associated with insulin resistance." (PMID 36922815, 2023). "From the point of view of the metabolic risk of obese patients, the adiponectin/leptin ratio seems to be of key importance, the value of which decreases with increasing insulin resistance." (PMID 36979669, 2023). "The SOCS3 protein is the main inhibitor of leptin and insulin signaling which causes cellular leptin and insulin resistance and dampens energy production." (PMID 37207231, 2023). "Since the associations have not yet been assessed and replicated in other studies, further studies are needed to confirm the associations of BDNF or LEP genetic variants with insulin resistance/weight gain in ASD patients treated with risperidone." (PMID 38375208, 2023). "Leptin-deficient mice exhibited myocardial hypertrophy, insulin resistance and altered substrate utilization, and Plin5 deficiency exacerbated myocardial hypertrophy in leptin-deficient mice." (PMID 37667357, 2023). "Although leptin concentrations increase with increasing fat volume, elevated levels of this hormone are associated with insulin resistance, inflammation, and AT lipolysis, probably through resistance to its catabolic effects." (PMID 37391843, 2023). "This is congruent with previous observations stating elevated leptin levels are associated with insulin resistance and T2DM development." (PMID 36901837, 2023).
Insulin resistance (continued). "Recent studies have shown that metabolic dysfunction, which is commonly observed in obese individuals and is characterized by inflammation, insulin resistance, leptin resistance, and hypertension, is a critical risk factor for depression." (PMID 37373992, 2023). "Lipin deficiency promotes insulin resistance, probably as a consequence of low leptin and adiponectin levels and impaired glucose absorption." (PMID 36837780, 2023). "Collectively these data powerfully indicate that CRP deficiency can improve insulin resistance and enhanced the influence of leptin on hepatic glucose kinetics and insulin signaling in PCOS rats." (PMID 37660067, 2023). "Excessive leptin causes triglyceride accumulation in adipose tissue, the pancreas, and the liver, triggering impaired insulin sensitivity, which leads to insulin resistance." (PMID 37174950, 2023). "BMI was positively associated with leptin, C-reactive protein and insulin resistance, and negatively associated with Free T4, progesterone and human chorionic gonadotropin." (PMID 36520252, 2023). "Insulin resistance, hyperglycemia, and changes in serum and gonadal concentrations of adipokines, like leptin, adiponectin, resistin, and ghrelin have been implicated as causes of male infertility in obese males." (PMID 38203349, 2023). "Increasing leptin in obese people causes an increase in insulin resistance and increases the incidence of stroke and myocardial infarction." (PMID 38028115, 2023). "Consumption of LPLM141 exhibited a significant amelioration in insulin resistance, which were mechanistically caused by downregulation of the serum leptin level and upregulation of hepatic IRS-1 and p-Akt protein expressions, in HFD treated rats." (PMID 37114144, 2023). "The adipocyte-derived peptide adipokine/hormone leptin in humans has been linked to adiposity and insulin resistance." (PMID 36984562, 2023). "The leptin/adiponectin ratio (a marker of insulin resistance) is associated with cardiometabolic risk factors in children." (PMID 36676079, 2023). "In mice, the dominant negative mutation exacerbates insulin resistance in the context of leptin-deficiency, demonstrating antagonistic roles for leptin and PPAR-γ in adipogenesis." (PMID 37051264, 2023). "In this context, recent studies have demonstrated that higher leptin levels are associated with insulin-resistance in newborns from mothers with GDM." (PMID 37497352, 2023). "For example, the AGE–RAGE axis can serve as a provoker of insulin resistance and altered leptin secretion, leading to an increased risk of diabetes and cardiovascular diseases’ prevalence." (PMID 37446161, 2023). "Leptin-deficient mice exhibit myocardial hypertrophy, which is closely associated with insulin resistance, altered substrate utilization, mitochondrial dysfunction, and lipid accumulation." (PMID 37667357, 2023). "A partial reduction of leptin content can promote weight loss and mitigate both leptin and insulin resistance in HFD-fed mice." (PMID 36558373, 2022). "The proposed mechanisms of causation include: insulin resistance; role of leptin in sympathetic activation; increased levels of inflammatory biomarkers such as IL-6; hypercoagulability; genetics." (PMID 36412616, 2022). "To verify the effect of Fetuin B on the association between leptin and insulin resistance, we performed mediation analysis in a population with central obesity." (PMID 35896788, 2022). "We found a positive correlation between HOMA-IR and leptin levels, along with other risk factors for insulin resistance, such as triglycerides, FPG, insulin levels, WC, and BMI." (PMID 36143007, 2022). "These inflammatory markers, such as tumor necrosis factor alpha (TNF-a), interleukin 6 (IL-6), C-reactive protein, and leptin, influence insulin resistance and growth hormone and cause an imbalance in protein synthesis, and lead to poor physical capacity." (PMID 35875029, 2022).
Insulin resistance (continued). "It has been indicated that low leptin levels have a significant effect on increasing the risk of developing insulin resistance and type 2 diabetes." (PMID 36248900, 2022). "Despite the global interest in understanding insulin resistance during pregnancy, most genetic studies on leptin and leptin receptor polymorphisms have been conducted in Western or East Asian populations." (PMID 36128550, 2022). "Via the complete loss of leptin the ob/ob mice develop a mild insulin resistance compared to other mouse models and corresponds to the observation that a nondiabetic phenotype is associated with a reduced level of SM in SAT in human obese patients." (PMID 35626717, 2022). "FGF21 and adiponectin are described as insulin sensitizers, and a high leptin level is associated with insulin resistance." (PMID 35327418, 2022). "Both leptin and resistin are pro-inflammatory adipokines overproduced during obesity and associated with insulin resistance." (PMID 35327570, 2022). "G2548A polymorphism in the LEP gene promoter has been associated with insulin resistance, leptin, and type 2 diabetes mellitus across different population, but has not been inclusively reported within the Malaysian population." (PMID 36381191, 2022). "Congenital leptin deficiency has been associated with hyperphagia, impaired thermogenesis, insulin resistance, hyperlipidemia, and central hypogonadism, which can be reversed by leptin treatment." (PMID 35198097, 2022). "This study also revealed that activation of IKKβ-NF-κB signaling by ER stress induces leptin and insulin resistance by affecting SOCS3, and these effects cause energy imbalance and weight gain." (PMID 36188456, 2022). "In the past, we have shown that pre-pregnancy BMI in normal uncomplicated pregnancies is positively associated with maternal leptin concentrations and insulin resistance indices." (PMID 35885635, 2022). "Obese people experience impaired control of appetite and the reward system caused by endocrine disturbances such as insulin resistance and decreased leptin release." (PMID 36429650, 2022). "Together with metabolic risk and insulin resistance improvements, leptin and adiponectin decrease were correlated with a decrease in BMI and increase in cardiorespiratory fitness." (PMID 35276833, 2022). "Several studies report that decreased levels of leptin and adiponectin are associated with insulin resistance and the development of diabetes." (PMID 36479221, 2022). "Since leptin is mainly secreted from adipose tissue, blood levels of leptin increase with women and higher insulin resistance, all of which are associated with an elevated risk of AD." (PMID 36329496, 2022). "In summary, intermittent fasting has shown positive effects on weight loss, in addition to reducing insulin resistance and favorably shifting the levels of leptin and adiponectin." (PMID 35276989, 2022). "While previous studies have explored the role of leptin in metabolic disorders, there is limited data on the association betweenLEP andLEPR gene polymorphisms and insulin resistance in pregnant Indian women." (PMID 36128550, 2022). "The adipokines leptin and resistin have also emerged as potential causes of insulin resistance, as they interfere with insulin receptor substrate-1 and lead to its degradation." (PMID 35885550, 2022). "Few studies have been conducted on the polymorphism of the leptin and adiponectin receptor genes responsible for insulin resistance and the development of MS and DM2." (PMID 36117520, 2022). "After surgery, ghrelin levels increase due to GH normalization and improved insulin sensitivity, but leptin levels also increase, which is associated with the development of insulin resistance." (PMID 35355553, 2022). "It mainly includes high-frequency keywords such as BMI, insulin resistance, metabolic syndrome, risk factor, leptin, insulin, and adiponectin." (PMID 36339176, 2022).
Insulin resistance (continued). "The insulin resistance and hyperglycemia of leptin-deficient ob/ob mice can be reversed by exogenous leptin treatment." (PMID 36046814, 2022). "The goal of this study was to determine the pattern of leptin gene and receptor polymorphism in insulin resistant and insulin sensitive pregnant women, as well as its relationship to insulin resistance." (PMID 36128550, 2022). "It had also been established that insulin resistance, circulating levels of leptin, and oxidative stress associated with endothelial cell function were strongly associated with CV death, and SGLT-2i inhibited all of these conditions." (PMID 35445086, 2022). "In line with results on leptin, leptin/adiponectin ratio, a suggested marker of insulin resistance, was also negatively associated with breast cancer risk in the present work." (PMID 35948877, 2022). "It was found that in patients with PCOS, elevated serum leptin level was associated with hyperandrogenemia and insulin resistance." (PMID 35355566, 2022). "The linear regression analysis confirmed that leptin was an independent risk factor for insulin resistance, even considering the creatinine level." (PMID 36143007, 2022). "HFD-fed models usually had enhanced production of systemic leptin and insulin, which was associated with leptin and insulin resistance, as well as metabolic disorder." (PMID 36558373, 2022). "Some studies indicated that the potential mechanisms of hepatic steatosis induced by CLA were insulin resistance and consequent hyperinsulinemia, which was closely associated with decreased adipokine (leptin)." (PMID 35382379, 2022). "Our previous and other studies have demonstrated that hot flashes are linked to metabolic disorders, such as insulin resistance and adiponectin/leptin imbalance and low-grade systemic inflammation." (PMID 36260646, 2022). "High adipose mass is associated with the increased production of aromatase, leptin and insulin resistance and dyslipidemia, all of which result in tissue damage." (PMID 36585675, 2022). "Adipose tissue dysfunction, marked by higher leptin and lower adiponectin levels, has been associated with insulin resistance and the incidence of T2D." (PMID 36014832, 2022). "There is a direct relationship between body fat levels, leptin, and insulin resistance, with the leptin receptor deficient db/db mouse presenting with alterations in lipid metabolism and liver function including steatosis." (PMID 36992750, 2022). "The circulating level of leptin has been reported to be reduced in cachectic patients, with a direct association with appetite and insulin resistance, which are two other hallmarks of cachexia syndrome." (PMID 36158184, 2022). "Leptin has also been linked to inflammation in the adipose tissue associated with and demonstrated to induce insulin resistance." (PMID 35739885, 2022). "Mice fed with a HFD presented a significant increase of leptin, and insulin concentrations, accompanied by a notable increase in HOMA-IR than the control, which were the hallmark features of leptin, and insulin resistance as well as metabolic disorders." (PMID 36558373, 2022). "For example, increased levels of leptin and resistin are associated with elevated caloric intake and insulin resistance." (PMID 35499991, 2022). "When these patients are treated with leptin replacement therapy, appetite is suppressed, energy expenditure is stimulated, weight loss occurs, and insulin resistance, blood glucose levels, and dyslipidemia are reduced." (PMID 35527735, 2022). "Down regulation of leptin contributes to insulin resistance and show a correlation to the risk of metabolic syndrome, and leptin modulate immune reactions." (PMID 33807712, 2021). "On the other hand, our previous investigations showed that leptin was positively associated with cardiovascular risk independent of body weight, increasing the risk of hypertension and insulin resistance and decreasing renal function." (PMID 34385686, 2021).
Insulin resistance (continued). "This adiposity replacement phenomenon is otherwise known as sarcopenic obesity and is associated with increased leptin levels and insulin resistance." (PMID 33355998, 2021). "Insulin resistance induced by congenital leptin deficiency also renders Igf2βKO females more hyperglycaemic compared to leptin-deficient controls." (PMID 33833312, 2021). "Maternal leptin levels are associated with gestational insulin resistance/sensitivity, assessed by intravenous glucose tolerance test or HOMA-IR in late pregnancy." (PMID 34884524, 2021). "Tumor necrosis factor α and leptin have also been implicated as contributors to insulin resistance and hyperglycemia in pregnancy." (PMID 34126994, 2021). "The concentration of leptin in blood in obese patients with dyslipidemia is high, causing signaling alteration, promoting the development of insulin resistance and T2D." (PMID 33572702, 2021). "Previous studies have reported that increased leptin levels are associated with insulin resistance and T2DM development." (PMID 34294853, 2021). "Leptin and adiponectin are associated with insulin resistance and MS in children and show anti‐inflammatory effects." (PMID 33532616, 2021). "Such early and significant muscle loss and atrophy are believed to be due to the presence of severe insulin resistance, hyperglycemia, loss of leptin signaling, metabolic derangements, and their consequent toxic effects on muscle growth and development." (PMID 34082690, 2021). "Leptin can cause insulin resistance and hyperinsulinemia through a variety of ways, and hyperinsulinemia and insulin resistance can cause excessive secretion of leptin, thus forming a vicious circle, leading to abnormal glucose and lipid metabolism." (PMID 34589546, 2021). "Insulin resistance and serum leptin levels were also associated with appendicular skeletal muscle loss in elderly and hemodialysis patients." (PMID 34578846, 2021). "Hyperleptinemia is a feature of other metabolic conditions and is associated with systemic insulin resistance, where insulin is a known leptin secretagogue." (PMID 33848268, 2021). "The presence of H. pylori was also associated with decreased adiposity, high levels of stomach leptin, and insulin resistance." (PMID 33953692, 2021). "Central obesity and insulin resistance are associated with hyperleptinemia, coupled with leptin resistance and reduced leptin transport across the blood–brain barrier (BBB) and into the hypothalamus and hippocampus." (PMID 33946540, 2021). "Previous studies have observed that weight loss among overweight or obese patients with T2D was consistently associated with a reduction of hemoglobin A1c, insulin resistance, and leptin levels, which involved in the pathogenesis of T2D." (PMID 35096931, 2021). "Hyperleptinemia is associated with insulin resistance and micro- and macrovascular diabetic complications, and leptin-mediated hypertension was suggested as one of the mechanisms of developing cardiovascular diseases." (PMID 34501456, 2021). "Since leptin insufficiency is associated with metabolic disease and insulin resistance, we would expect metabolic abnormalities in LEP/LEPR wt/-." (PMID 34448070, 2021). "Such sleep disturbance further disrupts key circadian rhythms, causing vicious cycles of induction and exacerbation of insulin resistance, and reciprocal changes in leptin and ghrelin secretion, which impair glycemic control." (PMID 33672896, 2021). "Leptin, adiponectin, and their ratio were associated with insulin resistance and other cardiometabolic comorbidities." (PMID 32337295, 2020). "Liver transplant recipients with insulin resistance and alterations in adiponectin and leptin are susceptible to hepatic steatosis and should be actively diagnosed and treated." (PMID 32728230, 2020).